MUC2 (mucin 2, oligomeric mucus/gel-forming)
Diseases named in the same sentence as MUC2 in open-access papers (continued):
Sharing a sentence is not in itself a finding about the gene and the disease.
colitis (continued). "Overall, the Muc2−/− mice fed the CO and MF diet exhibited multiple features of more aggressive colitis, whereas the MD presented with a milder form of the disease." (PMID 35471119, 2022). "In this study, Alcian blue staining showed that the goblet cells and secretion of MUC2 in the colon of the mice with colitis were substantially reduced compared with those in the control group." (PMID 35627006, 2022). "Impaired expression of Muc2 O-glycan and ER stress has recently been reported to lead to disruption of the colonic mucus barrier, colitis, and related cancers." (PMID 36010498, 2022). "In this study, we further investigate the relationship between the destruction of the MUC2-related mucus barrier and the colonic inflammation triggered by the TLR5/MyD88/NF-κB pathway in the TNBS-induced colitis model." (PMID 35571126, 2022). "The treatment of MAS maintained the expression of Muc2 in the DSS-induced colitis, which expressed higher levels of Muc2 than the DSS group (p < 0.05)." (PMID 36139747, 2022). "Microbial transfer to wild-type mice via littermate co-housing shows that colitis-associated microbiota rather than inflammation per se defines behavioral features in Muc2 colitis model." (PMID 36175462, 2022). "Decreased goblet cell count and thinning of the mucus layer, with a lowered expression of MUC2, are commonly seen both in patients with UC and in animal models of colitis." (PMID 36016685, 2022). "Consistently, along with ameliorated symptoms and histological damage, mice subjected to DSS-induced colitis receiving 5% red raspberry displayed a greater goblet cell density and increased mRNA levels of Muc2 and Klf4, and HES1 protein content." (PMID 35334805, 2022). "During DSS-induced colitis, the mRNA level of Muc2, a mucin protein that was primarily produced by goblet cells, was higher in Gsdmd-deficient mice than in WT mice." (PMID 34721422, 2021). "Eight articles focused solely on the relationship between MUC2 and colitis, whilst five articles studied MUC2 and a selection of other mucins in colitis." (PMID 33946184, 2021). "In the Il10−/− spontaneous colitis model, A. pulmonis colonization significantly downregulated gene expression of several intestinal barrier molecules including Muc2, ZO-1, and Occludin." (PMID 34814945, 2021). "On the animal level, genetic loss of Muc2 leads to spontaneous colonic inflammation and higher susceptibility to DSS-induced colitis." (PMID 34948435, 2021). "Treatment with CM-AcMSC significantly increased the expression of MUC2 and TJs and suppressed the production of pro-inflammatory cytokines in colonic tissues of colitis rats." (PMID 34604183, 2021). "As seen in a previous study, probiotic strain can stimulate MUC-2 expression in intestinal goblet cells and mitigate acute colitis in a mouse model." (PMID 33737918, 2021). "In the current study, we have shown that in absence of microbiota, intestinal inflammation, and epithelial ER stress are significantly alleviated in a Muc2 misfolding induced spontaneous colitis mouse model." (PMID 33645438, 2021). "In the colitis model, expression of the potential barrier-protective gene, Muc2, is enhanced upon administration of a Qa-1b agonistic peptide." (PMID 34911745, 2021). "Several studies have shown that the thickness of the mucus is decreased in wild-type mice with DSS-induced UC, while Muc2-deficient mice developed spontaneous UC and were more susceptible to DSS-induced colitis." (PMID 34658866, 2021). "Several of these common RNF20/RNF40/VDR targets were shown to be downregulated in experimental colitis, such as Muc2." (PMID 34088983, 2021). "Various mouse models of colitis, including mice deficient in Muc2, Tlr5, Il10, or DSS-induced colitis model, had bacteria penetrating into the otherwise impenetrable inner colonic mucous layer." (PMID 34814945, 2021).
colitis (continued). "The colonic tight junction proteins ZO-1 and mucin (MUC-2) were localized in the epithelial cell membrane of healthy intestines, but largely depleted in colitis mice." (PMID 34899735, 2021). "In contrast, Muc4-/- mice demonstrated resistance to DSS-induce colitis, which can be explained by compensatory upregulation of the Muc2 and Muc3 level." (PMID 34948435, 2021). "MUC2-knockout mice have been found to be more sensitive to DSS-induced colitis and presented with severely damaged mucosa, indicating that MUC2 plays an indispensable role in the gut barrier function." (PMID 33532501, 2021). "In fact, Muc4−/− mice challenged with DSS colitis have been found to have higher expression of both MUC2 and MUC3 compared to wild-type mice." (PMID 33013869, 2020). "Adequate goblet cells thus produce mucin (MUC2) in the colon are critical to the prevention of colitis." (PMID 33369455, 2020). "The muc2 has an anti-inflammatory and tumor suppressive role, and experiments with muc2 knockout mice have shown abnormal goblet cells followed by development of colitis and colorectal cancer." (PMID 33679713, 2020). "We propose that mitochondrial damage and metabolic shifts during chronic inflammation contribute to the leaky gut syndrome in Muc2 knockout animal model of colitis." (PMID 33273633, 2020). "They found that IL-18 treatment at an earlier stage of colitis changed colon length, reduced inflammatory infiltration, and increased Muc2 expression." (PMID 32466125, 2020). "Exacerbation of mucosal damage by HFDs, particularly saturated fats (e.g., palm oil), is also reported in murine spontaneous ileitis (Mdr1a-/-), and colitis (e.g., Muc2-/-, TNFare; defective translational control of TNF mRNA)." (PMID 33603741, 2020). "Mice with DSS-induced colitis displayed reduced levels of MUC-2 expression and mucin secretion, which is restored by low-dose IL-2 treatment." (PMID 32308767, 2020). "When colitis was induced, in all groups, the clear expression pattern of Muc2, Reg3b, and Reg3g was lost, but Clec7a, Clec4n, and Il22 mRNA expression was still increased in HSD- vs. CD-fed mice." (PMID 33339337, 2020). "We found a similar trend of higher circulatory iron levels in Muc2+/+ littermates after induction of long-term colitis with low dose DSS (0.75%) for 3 weeks; however total iron levels in the liver was not significant." (PMID 31980623, 2020). "Idebenone also improved the histopathology, immune parameters and clinical manifestations of colitis, and increased MUC2 levels." (PMID 32998266, 2020). "One of the widely used mouse models of IBD is Muc2 knockout mice that tend to develop spontaneous colitis followed by the formation of adenocarcinomas." (PMID 33273633, 2020). "It is possible that the DSS colitis stimulates increased Muc2 expression in an attempt to protect the intestine." (PMID 30873029, 2019). "Body weight, colon length, intestinal injury and expression of MUC2 and ZO-1 were recorded, detected and analyzed for evaluation of colitis severity." (PMID 30923519, 2019). "This study aimed to investigate changes in MUC2 expression, inflammation, and changes in lectin expression in colitis patients." (PMID 31198858, 2019). "It was concluded that in colitis there was a change in MUC2 expression due to changes in lectins accompanied by apoptotic defects." (PMID 31198858, 2019). "Decreased mucus production is also observed in other mouse models of colitis leading to increased epithelial contact with bacteria as observed in Muc2+/− mice." (PMID 30723224, 2019). "The MUC2, caspase-3, and lectin expressions were significantly lower in the colitis group than in the control group (p < 0.05)." (PMID 31198858, 2019). "Nonetheless, there is still controversy in the expression of MUC2 in colitis patients, in the form of decreased expression, as well as a moderate increase in MUC2 expression compared to controls." (PMID 31198858, 2019).
colitis (continued). "MUC-2 expression decreased significantly in the colitis group compared to the control group (p < 0.05)." (PMID 31198858, 2019). "Nr2f6-deficient mice are highly susceptible to DSS-induced colitis; mechanistically, NR2F6 directly binds to a consensus sequence at −2 kb of murine and human MUC2 promoter and transactivates Muc2 expression." (PMID 31139192, 2019). "Muc2 is the major secreted intestinal mucin and its absence in Muc2−/− mice leads to colitis, which starts in the distal colon and spreads to the proximal colon." (PMID 30723224, 2019). "During DSS colitis, Muc2 and Muc3 expression was selectively reduced in Nr2f6-deficient colonic scrapings whereas Muc1, Muc4 and Muc5ac expression was unaltered." (PMID 28779026, 2018). "In contrast to CEA CAM1, loss of MUC2 expression correlates to poor prognosis in CRC patients, and depletion of MUC2 in mice causes spontaneous colitis." (PMID 29414601, 2018). "To further explore the protection effect of Farrerol in experimental colitis, we investigated the expression of mucin-2 (MUC2) protein by immunofluorescence." (PMID 30011811, 2018). "Mice devoid of Muc2 show the disappearance of the inner mucus layer and develop spontaneous colitis resulting from the bacterial invasion of the colonic mucosa." (PMID 29619131, 2018). "Supplementation with the dipeptide alanine-glutamine, led to decreased expression of inflammatory mediators and increased expression of mucin 2 (MUC2) promoting mucosal recovery in the DSS-induced colitis mouse model." (PMID 28804483, 2017). "Muc2-/- mice develop colitis around four weeks of age and the abundance of Bacteroides pathobionts increased before histological signs of pathology." (PMID 28898292, 2017). "Mutations in the Muc2 gene lead to ER stress, inflammation, and spontaneously colitis due to accumulation of MUC2 precursor in the ER and reduction in mucin secretion." (PMID 29118753, 2017). "MUC13, a mucin implicated in gastrointestinal homeostasis, was upregulated in the LP of mice with DSS-induced colitis treated with ES, while MUC2, a major component of mucus, was upregulated in the IEC." (PMID 28191818, 2017). "MOS administration attenuated colitis-related increase of Coliforms, normalized colonic muc2 expression and attenuated local expression of proinflammatory cytokines IL-1a, IL1b, IL6, KC, G-CSF and MCP1 as well as toll-like receptor TLR4 and NLRP3 inflammasome." (PMID 27658624, 2016). "Induction of colitis decreased MUC2 expression, which was reversed by administration of IL-18, but not IL-1β." (PMID 27966619, 2016). "To assess the role of PKD2 in epithelial barrier function, we first analyzed the expression of ZO-1 and MUC2 in colon of mice with DSS-induced colitis." (PMID 27659202, 2016). "Expression of murine Btn and Btnl genes was examined in mouse models of spontaneous colitis (Muc2−/−) and intestinal tumorigenesis (ApcMin/+)." (PMID 27957327, 2016). "Using Muc2-/- mice, which lack a functional mucus barrier and develop spontaneous colitis, we show that colitic animals have reduced colon CD103+CD11b- DCs and increased CD103-CD11b+ phagocytes." (PMID 26121642, 2015). "The Muc2-/- spontaneous colitis model gives insights into how colitis affects iMP function and subsequent T cell responses, which increases our understanding of intestinal homeostasis and its disruption in inflammatory bowel disease." (PMID 26121642, 2015). "The data suggest that spontaneous colitis in Muc2-/- mice is progressive, starting distally and extending towards the caecum, which mimics human ulcerative colitis." (PMID 26121642, 2015). "The histologic damage in the colitis-inducing agent, dextran sulfate sodium (DSS)-treated Muc2-deficient mice are different compared with wild type and Muc2-heterozygous deficient mice, with many crypt abscesses." (PMID 26818460, 2015). "Here we use Muc2-/- mice that lack protective Muc2 mucin in the colon and develop spontaneous colitis with features resembling human ulcerative colitis." (PMID 26121642, 2015).
colitis (continued). "Consistent with this, Muc2-/- mice with extensive colitis had increased IL-17 in the distal and middle colon." (PMID 26121642, 2015). "Upregulation of claudin-1 following DSS induced colitis results in an upregulation of MMP-9 which triggered Notch signalling resulting in decreased MUC2 expression through decreased goblet cell differentiation." (PMID 25948887, 2015). "Muc2 was overexpressed in colonic epithelial cells, and genetic deficiency of this gene is sufficient to cause colitis and colorectal cancer, exerting the importance of Muc2 in the development of colitis and CAC." (PMID 24941171, 2014). "To determine the roles of aberrantly expressed miRNAs resulted from Muc2 absence in initiating colitis and facilitating colorectal cancer transformation, we used colonic epithelial cells instead of stromal cells or entire colon tissues for miRNA array." (PMID 24941171, 2014). "The knockout mouse of Muc2, which is one of the major components of mucus, has revealed mucin depletion and development of spontaneous colitis." (PMID 24498426, 2014). "Both TNF and MUC2 play a major role in the development of DSS-induced colitis via their involvement in epithelial barrier function, and they are altered before epithelial cell damage occurs." (PMID 23723167, 2013). "Muc2 knockout mice spontaneously developed a mild colitis and treatment with cytotoxic luminal agents like DSS led to severe colitis." (PMID 22514630, 2012). "Furthermore, EGT ameliorated DSS-induced colitis, reducing macrophage infiltration and restoring the expression of tight junction proteins ZO-1, Occludin and MUC2, confirming its broad anti-inflammatory and barrier-protective activities." (PMID 41530565, 2026). "The synbiotic FCT (fermented milk with L. gasseri 505 and C. tricuspidata) has demonstrated concurrent upregulation of MUC2, TFF3, and tight junction proteins (occludin, ZO-1), along with significant downregulation of TNF-α, IFN-γ, IL-1β, IL-6, and iNOS/COX-2 in colitis-associated cancer models." (PMID 41395459, 2025). "Tong and others found that bovine and human milk-derived EVs could upregulate the expression levels of Muc2, ZO-1, and Occludin to improve intestinal barrier function and reduce colitis in mice." (PMID 40361597, 2025). "According to reports, animals lacking Muc2 are more susceptible to bacterial invasion, leading to intestinal inflammation and possibly spontaneous colitis development." (PMID 39856883, 2025). "Previously published studies show that impairments in MUC2 folding, defects in O- and N-glycosylation, and aggregation of the non-glycosylated form of MUC2 in mice each cause hyper-susceptibility to colitis coupled with aberrant GC function." (PMID 40692013, 2025). "It is well established that regulating Muc2 is paramount when it comes to colitis, as Muc2 deletion leads to development of spontaneous colitis in mice, which is not seen in mice deficient in other mucins, such as Muc1 or Muc13." (PMID 38397081, 2024). "Alcian blue and periodic acid–Schiff (PAS) staining revealed that the number of mucus-producing goblet cells was severely diminished, and substantial amounts of Mucin2 (MUC2) were lost in the colon of DSS-induced colitis mice compared to those in the control group." (PMID 39458282, 2024). "Previous studies showed that MUC2 knockout mice could spontaneously develop colitis and have less resistance to the invasion of enteral pathogens." (PMID 39458282, 2024). "MUC2 is the first defense layer of the colon and plays a vital role in colitis and CAC development." (PMID 38979515, 2024). "The deletion of the MUC2 gene leads to the development of spontaneous colitis in a mouse model." (PMID 38500062, 2024). "Reduced colitis by modulating cytokines, miR-34a, MUC2, GLNAT7, and ANRIL." (PMID 39076514, 2024).
colitis (continued). "However, some researchers support the view that the protective effect of whey protein against colitis induced in rats is due to its high levels of threonine and cysteine, which stimulate MUC2 synthesis." (PMID 39064745, 2024). "Additionally, the number of colonic epithelial goblet cells was reduced, and the production of mucus and the expression of mucin 2 (MUC-2) protein were inhibited in colitis mice treated with HPAD and HSAD." (PMID 38233383, 2024). "Another recent study clearly demonstrated that mice devoid of St6galnac6, which is highly and selectively expressed in mouse colonic epithelia, develop spontaneous colitis because of the less lubricant mucus with the unidirectional Muc2 network structure due to the reduced sialylation." (PMID 39589551, 2024). "An increase in Muc-2 gene expression is assumed to reduce colitis." (PMID 37095161, 2023). "Similarly, mice models knocked out for the MUC2 gene (which codes for Mucin2, another component of the mucosal barrier) spontaneously develop colitis." (PMID 37512497, 2023). "By contrast, IL-18 treatment at a later stage of the disease enhanced inflammatory infiltration and reduced Muc-2 expression, decreased the function and quantity of goblet cells, suggesting the anti-inflammatory effect of IL-18 at the early stage of colitis-induced inflammation." (PMID 37383609, 2023). "Similarly, in our study, TNBS-induced colitis resulted in a reduction in the expression of Muc-2 and Muc-3, which are key constituents of the colonic mucus layer, and villin, a bioactive peptide involved in epithelial repair and regeneration." (PMID 38136191, 2023). "The authors mentioned that it is possible to induce colitis in mice by suppressing the MUC2 gene." (PMID 37512030, 2023). "In experiments on Strobilanthes cusia (Nees) Kuntze [Acanthaceae; indigo naturalis], treatment for 1 week could alleviate DSS-induced colitis in mice and increase the expression of E-cadherin, occludin, ZO-1, and MUC2." (PMID 37942490, 2023). "This altered sensitivity to disease observed in TgVil1-Itln1 may be a consequence of mucus layer thinning, similar to the spontaneous colitis reported in Muc2−/− mice and in gnotobiotic Il10−/− mice colonized with A. muciniphila." (PMID 36413219, 2023). "In addition, acetic acid can restore the decreased expression of MUC2 proteins in colonic crypts and repair the damaged mucus barrier, and butyric acid can alleviate colitis through enhancing IL-22 production." (PMID 37111225, 2023). "MUC2 expression is essential in suppressing the inflammatory response by blocking access of bacteria to the underlying epithelium, and the absence of Muc2 has been shown to predispose mice to the development of spontaneous colitis." (PMID 37174625, 2023). "In addition, it elevated the SCFAs production in the feces and colon and Mucin-2 (Muc2) mRNA levels in the colon in colitis mice." (PMID 36986258, 2023). "The disappearance of FCGBP and MUC2 during the restitutive phase of DSS colitis suggests that both molecules are tightly regulated and may have a long-lasting impact during tissue healing and in epithelial barrier function." (PMID 37359538, 2023). "Indeed, Muc2 knockout mice developed spontaneous colitis after 5 weeks of age and exhibited increased susceptibility to DSS-induced colitis." (PMID 35602503, 2022). "Similarly, FMT from SD mice, Aeromonas veronii colonization, and LPS treatment restored the SD-like goblet cells number and MUC2 protein decrease and colitis." (PMID 35355860, 2022). "Interestingly, the amino acid-based ED increased the protein expression of Muc2 in both normal mice and those with colitis." (PMID 36468853, 2022). "The increase in the abundance of Parabacteroides in the colon might be one of the reasons for the decrease in goblet cells and mucin MUC2 in the colon mucous layer of mice with DSS-induced colitis, as well as the increase in intestinal permeability." (PMID 35631210, 2022).